TNF (tumor necrosis factor)
Diseases named in the same sentence as TNF in open-access papers (continued):
Sharing a sentence is not in itself a finding about the gene and the disease.
Obesity (continued). "In conclusion and within the limits of this study, it was not possible to establish a positive link between CP and obesity in terms of differences in the levels of adiponectin, leptin and TNF-α between obese and NW subjects with and without periodontitis." (PMID 26330934, 2015). "Treatment of human subjects with anti-TNF antibodies, such as Infliximab or Etanercept, did not improve insulin resistance or improved obesity." (PMID 25918733, 2015). "Overexpression of TNF-α and TGF-β results in cell injury, accumulation of immune cells, inducing more proinflammatory cytokines and production of fibrosis-related proteins, which promote obesity-related disease development." (PMID 25984739, 2015). "The visceral adipose tissue expression levels of APN in normal group was greater than those in obesity and T2DM groups, and visceral adipose tissue expression levels of TNF-α and MCP-1 in normal group were lower than those in obesity and T2DM groups (P < 0.01)." (PMID 26273678, 2015). "Unlike “classic” pro-inflammatory mediators, for example TNF-α, IL-6 and C-reactive protein, T cell-derived cytokines, such as IL-17A, have not been extensively investigated in obesity." (PMID 26263971, 2015). "In this experiment, we confirmed that obesity prior to asthma could aggravate lung function and AHR, and systemic overexpression of TNF-α might be a typical mechanism to explain the exacerbated lung function." (PMID 25658739, 2015). "Given the pivotal role of IL‐1β and TNFα in nonpregnancy‐related obesity, we examined secretion and gene expression in gonadal fat depots." (PMID 25096554, 2014). "Similar results were confirmed by observational studies including early-RA patients, in whom both obesity and overweight confer a lower chance to obtain remission or low disease activity, irrespective of treatment with DMARDs or anti-TNF therapy." (PMID 25426122, 2014). "ABCA1 expression is reduced in patients with obesity-related metabolic diseases such as hypertension and T2DM, mouse models of insulin resistance and diabetes, and by pro-inflammatory mediators such as TNFα and CRP." (PMID 25045936, 2014). "TNFα has been reported to induce brown adipocytes apoptosis in primary culture, inhibit UCP-1 expression and mediate BAT atrophy in insulin resistance syndromes such as obesity and diabetes." (PMID 25144367, 2014). "We hypothesized that, in male rat pups, IUGR would increase TNFα, TNFR1, and components of the UPR (Hspa5, ATF6, p-eIF2α, and Ddit3) prior to the onset of obesity." (PMID 24804087, 2014). "In other systems, IL-17A synergizes with other cytokines including TNFα to promote changes in cell function and similar synergistic effects of TNFα and IL-17A may be necessary to drive AHR in obesity." (PMID 25309539, 2014). "Nevertheless, this increase in TNFα mRNA levels in VAT is not reflected in the serum where increased TNFα levels in sepsis were not further influenced by obesity." (PMID 25244356, 2014). "On the other hand, there is increased prevalence of obesity among patients with OSAS, and previous evidence suggests that adipose tissue can produce proinflammatory factors, such as C-reactive protein (CRP), tumor necrosis factor-α (TNF-α), interleukin-6 (IL-6), and interleukin-8." (PMID 25538852, 2014). "The plasma TAC levels were decreased and the serum TNFα levels were increased in sepsis although they were not influenced by obesity." (PMID 25244356, 2014). "Abundant studies have linked the increased production of inflammatory cytokines, such as tumor necrosis factor-α (TNF-α), interleukin (IL)-6, and certain adipokines, during the inflammatory process to obesity, as well as to the development of insulin resistance." (PMID 24347527, 2014). "In conclusion, our results show that the HP2/HP2 genotype is associated with elevated TNF-α and IL-6, but not with hsCRP, levels in obese subjects, suggesting that the functional differences of HP subtypes could be associated with different outcomes of obesity." (PMID 24868113, 2014).
Obesity (continued). "Uysal and colleagues reported that mice lacking TNF-α were resistant to obesity-induced insulin resistance." (PMID 21826136, 2012). "Elevated TNF-α mRNA expression has been shown in ob/ob, tub/tub, and KKA mice, and Zucker fa/fa rats as well as transgenic model of obesity/insulin resistance created by ablation of brown adipose tissue (BAT) via a bacterial toxin gene driven by the UCP promoter." (PMID 23056223, 2012). "Chronic inflammation in T2D initiates with states of obesity, hyperglycemia, insulin resistance, and the overexpression of proinflammatory proteins like CRP and cytokines (IL-1β, IL-6, and tumor necrosis factor-alpha (TNF-α))." (PMID 23316349, 2012). "Here, we provide evidence that adding one step more in obesity complications such as T2D-MO group, TNFα and JNK expression did not experiment any significant increase in comparison with the previous stage, high insulin resistance." (PMID 23110196, 2012). "They did not accompany the expected increases in TNF-α, whose circulatory levels are known to generally increase with the degree of obesity." (PMID 23173044, 2012). "In another study, within 2–6 weeks of HFD, CONV but not GF mice showed an increase in TNFα in the ileum, demonstrating a strong correlation between gut microflora and the degree of obesity." (PMID 23091640, 2012). "IPostC-induced cardioprotection was evident in the modestly obese TNF-WT mice and also in the diabetic TNF-WT mice, suggesting that the presence of obesity/diabetes did not alter the cardioprotective signalling cascade activated by IPostC." (PMID 23125848, 2012). "Resident macrophages in the adipose tissue produce cytokines, such as tumour growth factor (TGF)-β and tumour necrosis factor (TNF)-α, that also up-regulate PAI-1, indicating that the increase in PAI-1 occurs parallel to the obesity-induced development of T2DM." (PMID 23249721, 2012). "In this article, tumor necrosis factor-α (TNF-α) was shown to be constitutively expressed via adipose tissue, to be hyperexpressed in obesity, and to mediate insulin resistance in the major animal models of obesity." (PMID 22531046, 2012). "AP thus reduces hyperglycemia and hyperinsulinemia, not simply through alleviated obesity, but through increased adiponectin secretion and suppressed TNF-α secretion in white adipose tissue, and increased GLUT4 expression in skeletal muscle." (PMID 21799697, 2011). "Additionally, mice with deletion of the TNF-α gene, TNF-α converting enzyme or receptors for TNF-α are partially resistant to diet induced obesity and insulin resistance." (PMID 20808947, 2010). "However, compared to cachectic and normal-weight COPD patients, those with obesity had median values of adipose tissue expressions of CD68 higher by 240% and 89%, and of TNF-α by 88% and 109%, respectively." (PMID 21197447, 2010). "In addition, increased expression of inflammatory mediators such as TNF-α, PAI-1, and leptin was detected in human obesity." (PMID 20414465, 2010). "Therefore, to prevent obesity-related inflammation, it is important to decrease the production of obese-adipose-tissue-derived proinflammatory factors such as MCP-1 and TNF-α." (PMID 20613991, 2010). "TNF-α was overexpressed in white adipose tissue (WAT) in obese an insulin-resistance states; mice lacking the TNF-α ligand or the p55 TNF receptor were partially protected from obesity-induced insulin resistance." (PMID 20107539, 2009). "In the present study we did not observe differences of serum concentrations of TNF-α, IL-6, and leptin between depressive and nondepressive patients with obesity." (PMID 19587822, 2009). "Indeed, a recent report indicates that obesity induces a subset of adipocytes to express both TLR2 and TNFα and exposure of adipocytes to zymosan triggers expression of TNFα." (PMID 19348674, 2009).
Obesity (continued). "Recently, it has been shown that TNF-α might positively autoregulate its own synthesis in adipose tissue, which might contribute to the maintenance of the elevated TNF-α observed in obesity." (PMID 19333447, 2009). "Resistin mRNA expression is increased in PBMC from DM2 women, together with increased expression of the inflammatory cytokines IL-1β, TNF-α, and IL-6, independent of obesity." (PMID 19125180, 2008). "Inflammatory cytokines such as tumor necrosis factor α (TNF α) and interleukin (IL)-6 are produced by adipocytes as well as by monocytes and macrophages, and they circulate at increased levels in individuals with obesity." (PMID 15578112, 2004). "Obesity-related chronic inflammation might promote tumor by releasing pro-inflammatory factors, such as IL-6 with anti-apoptotic and cell proliferation effect via JAK2 and PI3K/AKT, as well as TNF-α with anti-apoptotic effect via NF-kB." (PMID 40933888, 2025). "Furthermore, the perivascular adipose tissues (PVAT) in obese subjects exhibit impaired vasodilatory response to TNF-α and IL-6, which was reversed by anti-TNF-α monoclonal antibody, infliximab, highlighting the role of PVAT in regulating inflammation in obesity." (PMID 40004172, 2025). "Since TNF-α is mainly released by adipocytes, it could increase locally in obesity rather than being systemically elevated in the plasma." (PMID 41463113, 2025). "Even though the impact of obesity on the effectiveness of TCZ in RA remains controversial, the response to this drug is not significantly affected by weight or BMI, contrary to other biologic therapies, such as TNF inhibitors, making it a viable treatment option for overweight or obese RA patients." (PMID 40066438, 2025). "Additionally, chronic inflammation and elevated chemerin levels in obesity may contribute to reduced GLP-1 secretion, potentially through TNF-α-induced suppression." (PMID 40564199, 2025). "Additionally, an eight-week trial of late TRE with longer fasting durations (18 and 20 h) did not alter TNF-α or IL-6 compared to a control in adults with obesity." (PMID 39861451, 2025). "The model exhibits pronounced cardiometabolic dysfunction, including obesity, insulin resistance, dyslipidemia, QTc prolongation, reduced QRS amplitude, and elevated markers of myocardial injury (Troponin T, CK-MB) and systemic inflammation (IL-6, IL-1β, TNF-α) (p < 0.05)." (PMID 41309777, 2025). "In obesity, the adipose tissue functions as an active endocrine organ, secreting components of the RAAS, including angiotensin II and various pro-inflammatory cytokines, such as IL-1β, IL-6 and TNF-α and adipokines, contributing to chronic, low-grade inflammation and IR." (PMID 41020888, 2025). "This study revealed elevated IL-6 and TNF-α mRNA levels in the group with obesity compared to the one without, indicating that obesity alone may contribute to increased marker levels." (PMID 40004007, 2025). "Importantly, local WAT inflammation can induce regional insulin resistance through cytokine release (e.g., IL-1β, TNF, IL-6) without requiring systemic cytokine elevation, underscoring a paracrine component of muscle–adipose crosstalk in obesity." (PMID 41002965, 2025). "As expected, patients with obesity (Groups II and III) showed significant elevations in plasma levels of triglycerides, nonesterified fatty acids, and inflammatory markers such as CCL2/MCP‐1, TNF‐α, plasma endotoxin (LPS), and LEP, along with a very significant increase in adipocyte size." (PMID 40518865, 2025). "Alongside these, inflammatory cytokines such as tumor necrosis factor-alpha (TNF-α), interleukin-6 (IL-6), and C-reactive protein (CRP) are significantly influenced by changes in adipose tissue dynamics and play a central role in the development of obesity-related complications." (PMID 40710568, 2025).
Obesity (continued). "Another important aspect is the increased macrophage population on the placenta of women with obesity compared to pregnant women with normal weight, characterized by increased CD14+, CD68+, and CD11b+ markers, as well as increased gene expression of cytokines IL‐1, TNF‐α, IL‐6." (PMID 41452351, 2025). "Additionally, obesity increases the acetylation of H3K9 and H3K18 lysine in the TNF promoter." (PMID 40265287, 2025). "The results of our study revealed that concentrations of TNF-α and IL-6 decreased significantly after resuscitation in BRS and usage of PEEP, suggesting that the combined use of the two measures could reduce inflammatory response in patients with obesity." (PMID 39722113, 2025). "Compared with non-obese patients with PCOS, those with obesity demonstrated more severe inflammatory responses, including increased levels of IL-6, TNF-α, neutrophil-to-lymphocyte ratio (NLR), high-sensitivity C-reactive protein (hs-CRP), and mean platelet volume (MPV) levels." (PMID 41239503, 2025). "Likewise, in females with obesity, vaccinated mice had significantly lower levels of eotaxin, GM-CSF, GRO-α, IL-1β, IL-2, IL-5, IL-6, IL-12p70, IL-17A, IL-18, IP-10, MCP-1, MCP-3, MIP-1α, MIP-1β, MIP-2α, and TNF-α compared to unvaccinated controls." (PMID 41488663, 2025). "Importantly, biomarkers such as CRP, IL-6, TNF-α, and leptin are frequently elevated in individuals with overweight or obesity independent of dietary exposures." (PMID 41010537, 2025). "Furthermore, chronic TNF-α exposure to intestinal L cells decreases GLP-1 secretion and anti-TNF-α antibody; etanercept treatment reverses this effect in male mice with high fat diet (HFD)-induced obesity, which enhances the ageing process." (PMID 40592472, 2025). "In the state of obesity, macrophages are polarised into pro-inflammatory M1, nitric oxide synthase 2 (NOS2) is activated, and reactive oxygen species such as NO, CD11c are produced, as well as tumor necrosis factor alpha (TNF-α), IL-6, IL-1β, IL-12, and monocyte chemotactic protein are secreted." (PMID 41301704, 2025). "APLN shares a close relationship with TNF α expression in adipose tissue, which has led to its consideration as a potential bridge mediator between inflammation and insulin resistance in obesity, though body-mass is likely not a major determinant of its circulating forms." (PMID 40182840, 2025). "Obesity and SARS-CoV-2 infection stimulate a significant inflammatoryenvironment, and in obesity, there is the emission of inflammatory factors, mainlyTumor Necrosis Factor Alpha (TNFa) (related to insulin resistance and diabetes) andinterleukins 1 and 6 by adipose tissue." (PMID 40762988, 2025). "During the early stages of obesity, secreted CTRP6 may contribute to a pro-inflammatory environment by enhancing TNF-α secretion and NO production from adjacent resident macrophages, while concurrently suppressing their M2-associated gene expression, including Mrc1 and Pparg." (PMID 41159061, 2025). "The expression and secretion of many adipokines, such as leptin, resistin, tumor necrosis factor-α (TNF-α), interleukin-6 (IL-6), C-C motif chemokine ligand 2 (CCL2), CXC motif chemokine ligand 5 (CXCL5), and angiopoietin-like 2, are up-regulated in AT during obesity." (PMID 40076419, 2025). "In conditions such as obesity, aging, insulin resistance, dyslipidemia, or chronic oxidative stress, PVAT undergoes phenotypic switching, adopting a pro-inflammatory profile leading to increased secretion of leptin, IL-6, and TNF-α, while decreasing adiponectin levels." (PMID 40943241, 2025). "Notably, berberine can promote the differentiation of brown preadipocytes via the AMPK-PRDM16 axis, inhibit TLR4/TNF-α-mediated inflammatory responses, and reduce the expression of iNOS and COX-2, thereby enhancing thermogenesis and alleviating obesity through improved inflammation." (PMID 40362407, 2025).
Obesity (continued). "In addition, CRP regulates the expression of key adipokines and inflammatory mediators, including adiponectin, TNF-α, leptin, IL-6, and PPAR-γ, which may underpin its involvement in insulin resistance, obesity, and metabolic syndrome." (PMID 40001459, 2025). "Six weeks of wheel cage exercise in mice with diet-induced obesity (DIO) reduces expression of inflammatory markers such as TNF-α in the vWAT, while 12 weeks of aerobic and resistance training reduces circulating levels of TNF-α in mice with high-fat diet (HFD)-induced glucose intolerance." (PMID 40522819, 2025). "Finally, in order to demonstrate that the proposed model does the absence of over-prediction problems, we additionally selected a response for analysis, i.e., tumor necrosis factor-alpha (TNF-α), which is not directly related to obesity." (PMID 38873138, 2024). "Moreover, the increased fatty acids, lipopolysaccharides, and TNF-α can reduce the activities of protein kinase B (AKT) and AMPK, and, consequently, obesity ultimately leads to a reduction in the glucose uptake and lipid oxidation capacity of skeletal muscle, thereby exacerbating IR." (PMID 39858415, 2024). "In a meta-analysis of 48 prospective non-randomized studies, the authors reported that BS decreases the low-grade inflammation associated with obesity as measured by C-reactive protein (CRP) and interleukin 6, but not by tumor necrosis factor α, after pooling groups at 6 and 12 months follow-up." (PMID 39574780, 2024). "Additionally, BMI was used instead of waist circumference to assess obesity, and direct measurements of cytokines like IL-6 and TNF-α were not performed, limiting mechanistic insights." (PMID 39070321, 2024). "Additionally, obesity, asignificant factor in the development of T2DM, reduces the levels of adiponectin,a hormone that normally inhibits proinflammatory cytokines such as tumor necrosisfactor alpha (TNF-α) and interleukin 6 (IL-6)." (PMID 39742220, 2024). "IL-1b, IL-6, and TNF were not significantly regulated in monocytes of people with obesity at the investigated time points but it would be interesting to take a closer look pro-inflammatory potential of the lipid droplet positive monocytes in further studies or in a time series-dependent analysis." (PMID 39050851, 2024). "Obesity may contribute to OME through the following mechanisms: alterations in cytokine levels, such as IL-6, TNF-α, and fibrinogen activator inhibitor-1 (FAI-1); alterations in host immunity; induction of gastroesophageal reflux; and alterations in pharyngeal tube structure." (PMID 38440649, 2024). "Adipose tissue remodeling during obesity provides a plethora of intrinsic and extrinsic signals capable of triggering an inflammatory response and activation of cell signings, such as the JNK and NF-kB signaling pathways and the target genes, e.g., IL-6, TNFα, interferons, and MCP-1." (PMID 38541912, 2024). "HFD-induced obesity in C57BL/6 mice resulted in ER stress, intracellular free cholesterol accumulation, lipogenesis, NF-κB signaling, and a proinflammatory secretion profile of adipokines (resistin, TNF-α) in hypertrophic adipocytes, as well as systemic dyslipidemia and hyperglycemia." (PMID 39063184, 2024). "Moreover, network construction produced similar results: Rumonococcus, Lachnospiraceae_NK4A136-group, Prevotellaceae_NK3B31_group, and Clostridium_sensu_stricto_1 were involved in the accumulation of IL-1β, TNF-α, MG,AGEs, TG, AgRP, and SOCS3 for the development of obesity." (PMID 38659208, 2024). "In children with obesity, FFA and adipokines (e.g., leptin) secreted by enlarged adipocytes promote the differentiation of monocytes to proinflammatory macrophages in adipose tissues, leading to the production of inflammatory cytokines including TNF-α and IL-6." (PMID 40302954, 2024).